EDNRA (endothelin receptor type A)
Diseases named in the same sentence as EDNRA in open-access papers (continued):
Sharing a sentence is not in itself a finding about the gene and the disease.
tumor (continued). "Multivariate analysis revealed that EDNRA expression, tumor status, age, and primary therapy outcome influenced patient prognosis." (PMID 35517422, 2022). "From the TIMER web resource, the association between CDH11, COL6A3, EDNRA, and SERPINF1 immune signatures and tumor purity or numerous vital immune cells was revealed." (PMID 36595851, 2022). "The high expression level of EDNRA was essentially identified with tumor grade (P = 0.003), depth of invasion (P = 0.019), and lymphatic metastasis (P = 0.001) in GC patients." (PMID 34663825, 2021). "And 7 tumor-infiltrating immune cells were significantly correlated with EDNRA expression, among which macrophases M2 and mast cells rest were positively correlated with EDNRA expression." (PMID 34663825, 2021). "Intriguingly, in xenografts, the BRAF inhibitor/bosentan combination treatment led to a significant suppression of EDNRA expression within the residual tumours, which correlates with the drop in AXL expression." (PMID 28606996, 2017). "So far, most reports have focused on the role of EDN1 binding to EDNRA and its effects on tumour growth and neo-angiogenesis." (PMID 19527488, 2009). "Thoroughly understanding the crosstalk between EDNRA signalling and other pathways could reveal opportunities for synergistic inhibition with enhanced an‐tumour effect and potentially therapeutic effects." (PMID 40245183, 2025). "Furthermore, EDNRA was shown to have a strong relationship with the tumour stages of BLCA, BRCA, KICH, KIRC, LIHC, TGCT, and UVM." (PMID 39601333, 2024). "EDNRA antagonists can inhibit the growth and migration of tumour cells." (PMID 39601333, 2024). "This suggests that EDNRA is closely related to immune regulation, and that tumour patients with high EDNRA levels might exhibit an immunosuppressive state." (PMID 39601333, 2024). "EDNRA may be an important target in tumour immunotherapy and provide new insights for tumour immunotherapy." (PMID 39601333, 2024). "Numerous studies have indicated the imperative role of EDNRA in tumour immunity." (PMID 39601333, 2024). "First, we investigated the effect of EDNRA expression on tumor immunity." (PMID 35265193, 2022). "Furthermore, increased EDNRA expression in CRC patients is correlated with increased tumor grade and reduced patient survival." (PMID 32194414, 2020). "For instance, EDNRA, either independently or in combination with other biomarkers, was reported to be able to predict benign and malignant tumors from borderline tumors, tumor subtype classification and classification of tumors related to cell plasticity." (PMID 26100469, 2015). "In addition, patients with high expression of EDNRA might be resistant to the treatment of several anti-tumor drugs." (PMID 35517422, 2022). "EDNRA regulates its own expression and that of EDN1 through the STAT3 signalling pathway, creating a positive feedback loop that promotes tumour growth and metastasis." (PMID 39601333, 2024). "The correlation between EDNRA expression and immune infiltration was analysed by tumour immune estimation resource (TIMER) and tumour‐immune system interaction database (TISIDB)." (PMID 39601333, 2024). "Meanwhile, EDNRA, PRRX1, EMP1, AKR1B1, and SULF2 exerted an important role in cancer progression in other tumor types." (PMID 36816947, 2023). "The addition of macitentan to the BRAF inhibitor reduced the expression of EDNRA within the tumours, suggesting that through its affinity for EDNRA macitentan targets the AXL/EDNRA‐expressing cells." (PMID 28606996, 2017). "All these molecules are known to be involved in cancer process, some being identified as tumour suppressor genes (e.g. GPR54 and CLDN23) and others related to angiogenesis (e.g. CXL1 and EDNRA) or cell migration capacities (e.g. PLAU)." (PMID 17406368, 2007). "Hence, the potential mechanism of EDNRA in the TME was explored via TCGA pan‐cancer approach, hoping to discover new targets for immunotherapy of different tumours." (PMID 39601333, 2024).
tumor (continued). "Furthermore, in cluster 5, the upregulation of the endothelin receptor A (EDNRA) gene may have enhanced the pleiotropic effects of its ligand, endothelin-1, which is known to regulate EMT, angiogenesis, and immune response and has been implicated in drug resistance in various tumor types." (PMID 38999963, 2024). "Moreover, high levels of EDNRA were observed in BRCA, COAD, KIRC, LIHC, STAD, and THCA, and matched tumour and normal tissues were examined in TCGA pan‐cancer." (PMID 39601333, 2024). "CDH11, COL6A3, EDNRA, and SERPINF1 were all negatively correlated with tumor purity." (PMID 36595851, 2022). "We therefore assessed EDNRA expression in the A375 xenografts and found that although it was expressed at much lower levels than EDNRB, its expression was up‐regulated in BRAF inhibitor‐treated tumours." (PMID 28606996, 2017).
cancer (84 papers, 2003 to 2026). A tumor composed of atypical neoplastic, often pleomorphic cells that invade other tissues. "EDNRA was evidently associated with TCGA pan‐cancer, including mast cells, CD4+ T cells, NK cells, macrophages, monocytes, dendritic cells, plasma cells, and CD8+ T cells." (PMID 39601333, 2024). "We found high expression of GEM and EDNRA to be significantly associated with a decrease in cancer-specific survival, when analyzing the protein expression on a cohort of 368 patients." (PMID 25175477, 2014). "High expression of GEM (P = 0.033; HR = 1.46) and EDNRA (P = 0.046; HR = 1.60) were significantly associated with decreased cancer-specific survival." (PMID 25175477, 2014). "Immunohistochemical analysis of 368 tumors from cystectomized patients showed high expression of GEM (P = 0.033; HR = 1.46) and EDNRA (P = 0.046; HR = 1.60) was significantly associated with decreased cancer-specific survival." (PMID 25175477, 2014). "For instance, TNC was shown to stimulate cancer cell proliferation by inducing EDNRA, the gene encoding the receptor for endothelin-1, and by preventing cells from adhering to fibronectin." (PMID 22481923, 2012). "While we have shown significant effects of EDNRA modulating cancer cell behaviours, we cannot track the dynamic changes of the signalling network." (PMID 40245183, 2025). "ABT‐627, the specific inhibitor of EDNRA, shows significant efficacy by modulating the proliferation of cancer cells and activating both intrinsic and extrinsic apoptotic pathways." (PMID 40245183, 2025). "The potential role of endothelin receptor A (EDNRA) in cancer immunotherapy has been demonstrated; however, the mechanism of its therapeutic value remains to be investigated." (PMID 39601333, 2024). "DMS114 cells with resistance to nintedanib (a kinase inhibitor used to block cancer growth) (DMS114/NIN) portrayed an amplified expression of EDN1 and EDNRA, encoding ET-1 and ETAR, respectively." (PMID 38540124, 2024). "The predictive function of EDNRA in TCGA pan‐cancer was then determined using a univariate Cox regression assessment." (PMID 39601333, 2024). "Potential pathways with EDNRA involved in TCGA pan‐cancer were predicted using Kyoto Encyclopedia of Genes and Genomes (KEGG) pathway database‐based GSEA." (PMID 39601333, 2024). "EDNRA was more prominently overexpressed in cancer tissues than in adjacent normal tissues (P < 0.001)." (PMID 35517422, 2022). "Endothelin ligands (ET-1, ET-3) and receptors (EdnrA, EdnrB) form the endothelin axis, which participates in diverse biological processes including development, inflammation and cancer." (PMID 26061883, 2015). "Atrasenatan, targeting EDNRA, is capable of inhibiting proliferation and cancer growth-promoting processes." (PMID 19527488, 2009). "Combined targeting the network of EDNRA signalling might achieve more effective cancer treatment than monotherapy approaches." (PMID 40245183, 2025). "Furthermore, EDNRA‐related immunomodulators and dynamic immune biomarkers were assessed to determine EDNRA's function of EDNRA in pan‐cancer and provide novel insights into the underlying mechanisms influencing TME and cancer immunotherapy." (PMID 39601333, 2024). "First, EDNRA's prognostic function of EDNRA in the TCGA pan‐cancer was established." (PMID 39601333, 2024). "The EDNRA gene is involved in cellular processes related to cancer development and progression." (PMID 39275097, 2024). "EDNRA expression in different cancer types were performed via qPCR." (PMID 39601333, 2024). "In the case of EDNRA, its high expression may result from a reduction in the activity of miR-30a-5p, miR-30c-5p, miR-30d-5p, and miR-30e-5p in G1 cancer." (PMID 36542159, 2023). "Hence, the role and correlation of EDNRA in the STAD microenvironment possibly promote cancer cell growth in STAD and therefore lead to the poor prognosis of STAD patients." (PMID 35517422, 2022).
cancer (continued). "Then, we examined EDNRA expression in 375 cancer tissues and 32 adjacent normal tissues in TCGA." (PMID 35517422, 2022). "Therefore, EDNRA was identified as an imperative gene in cancers." (PMID 39601333, 2024). "In addition, the combined meta-analysis identified three additional cancer risk variants (rs77753011 at RPH3A on 12q24, P = 5.5 × 10−15; rs36079339 at AIDA on 1q41, P = 3.9 × 10−10; rs2059904 at EDNRA on 4q31, P = 1.2 × 10−8), of these two were pleiotropic associations." (PMID 37340002, 2023). "Pro-fibrotic fibroblasts were transcriptionally similar to cancer associated fibroblasts and expressed high levels of collagens and periostin (POSTN), thymocyte differentiation antigen 1 (THY-1), and endothelin receptor A (EDNRA) predicted to be driven by a RUNX1 gene regulatory network." (PMID 36747878, 2023). "Within the superfamily of G protein-coupled receptors (GPCRs), the endothelin receptor type A (ETAR) and type B (ETBR) play critical roles in numerous physiological and pathological conditions, including fibrosis and cancer." (PMID 39985042, 2025). "The correlation analysis of 24 immunosuppressants indicated that EDNRA was positively correlated with ADORA2A, CSF1R, KDR, TGFB1, and TGFBR1 in cancers, including BLCA, CHOL, ESCA, READ, and STAD." (PMID 39601333, 2024). "It has been verified that the EDNRA, JAK–STAT, and TGF‐β signalling pathways are involved in cancers." (PMID 39601333, 2024). "Therefore, EDNRA may affect pan‐cancer immunotherapy response." (PMID 39601333, 2024). "To understand the role of EDNRA in STAD pathogenesis, we assessed EDNRA expression levels in STAD between different cancers and adjacent normal tissues using data from The Cancer Genome Atlas (TCGA) database." (PMID 35517422, 2022). "EDNRA and EDNRB have also been found expressed in endothelial cells in different human tumors and a role in angiogenesis and cancer metastasis has been reported." (PMID 29349517, 2018). "The possible functional roles of EDNRA (endothelin receptor type A) and GEM (GTP binding protein overexpressed in skeletal muscle) in cancer progression and metastasis are currently unclear." (PMID 25175477, 2014). "The interplay between TNC, endothelin receptor type A (EDNRA), integrin α5β1, fibronectin, syndecan-4, and tropomyosin 1 has been reported to particularly contribute to TNC-induced cell proliferation in cancer via the activation of various signaling pathways." (PMID 22481923, 2012). "Hence, there is a potential impact of EDNRA expression on pan‐cancer TME and the impact of EDNRA on cancer prognosis." (PMID 39601333, 2024). "Although direct evidence linking the regulation of EDNRA expression to KIRP therapy is lacking, its high expression and critical regulatory roles across various cancers warrant further investigation as a therapeutic target for KIRP." (PMID 41515956, 2025).
cardiovascular diseases (13 papers, 2012 to 2026). "Endothelin-1, acting through the activation of EDNRA, is a potent vasoconstrictor with a well-established role in cardiovascular diseases." (PMID 40175777, 2025).
infection (7 papers, 2016 to 2025). The state of being infected such as from the introduction of a foreign agent such as serum, vaccine, antigenic substance or organism. "After adjustment for the potential confounders, sex, age, and time since infection, we found in addition to CHRM5-Ab significant differences with higher levels of AABs against CHRM1 and F2R/PAR-1 while lower levels of ADRB1, CHRNA1, and EDNRA in PCS/ME/CFS than in PCS/non-ME/CFS groups." (PMID 36238301, 2022).
EDNRA also shares sentences with these, for which no sentence is quoted: pulmonary hypertension (19 papers); prostate carcinoma (12); heart failure (11); kidney diseases (10); chronic kidney disease (7); preeclampsia (6); vasculopathy (6); focal segmental glomerulosclerosis (5); glioblastoma (5); ischemia (5); kidney damage (5); lung carcinoma (5); type 2 diabetes (5); kidney (4); mandibulofacial dysostosis (4); Sepsis (4); Stroke (4); subarachnoid hemorrhage (4); breast adenocarcinoma (3); Cerebral ischemia (3); cervical cancer (3); chronic heart failure (3); Cognitive impairment (3); Insulin resistance (3); myocardial ischemia (3); myocarditis (3); osteosarcoma (3); renal cell carcinoma (3); rheumatoid arthritis (3); systemic lupus erythematosus (3).
A further 124 diseases each share a sentence with EDNRA in 2 papers or fewer.